PLK1 (polo like kinase 1)
Diseases named in the same sentence as PLK1 in open-access papers (continued):
Sharing a sentence is not in itself a finding about the gene and the disease.
osteosarcoma (continued). "More importantly, in vivo delivery of lentiviral vectors targeting PLK1 substantially reduced osteosarcoma xenograft growth in a subcutaneous nude mouse model." (PMID 38780513, 2024). "In summary, these findings demonstrate that hfCas13d‐mediated PLK1 suppression is capable of substantially attenuating the in vivo tumour growth of osteosarcoma xenografts, potentially through the regulation of Smad3 activity." (PMID 38780513, 2024). "With effective PDX models of primary and recurrent osteosarcoma patients, we provided further clinical-relevant evidence for PLK1 targeted therapies and demonstrated the high specificity of Volasertib as a promising clinical candidate." (PMID 37419907, 2023). "PLK1 knockout substantially inhibited proliferation of osteosarcoma cells in vitro and the tumor growth of osteosarcoma xenograft in vivo." (PMID 37419907, 2023). "Considering the great potential in its therapeutic value, we further investigated the role of PLK1 in osteosarcoma using CRISPR knockout and a specific inhibitor Volasertib that has undergone multiple clinical trials." (PMID 37419907, 2023). "In order to exclude no-specific effects of inhibitor, we first investigated the role of PLK1 in SJSA-1 and 143B osteosarcoma cells by deleting PLK1 using two independent PLK1 sgRNAs from the kinome-wide CRISPR-Cas9 screens." (PMID 37419907, 2023). "Volasertib, a potent experimental PLK1 inhibitor, can effectively inhibit the growth of the osteosarcoma cell lines in vitro." (PMID 37419907, 2023). "Using kinome-wide CRISPR-Cas9 knockout screens, we systematically revealed a cohort of kinases essential for the survival and growth of human osteosarcoma cells, in which Polo-like kinase 1 (PLK1) appeared as a specific prominent hit." (PMID 37419907, 2023). "We further investigated the role of PLK1 in osteosarcoma by inhibiting its activity in osteosarcoma cell lines with Volasertib." (PMID 37419907, 2023). "We show here that Volasertib-based therapy is effective and specific in inhibiting osteosarcoma growth both in vitro and in vivo, thus facilitating further development of PLK1 targeted therapies." (PMID 37419907, 2023). "Among a cohort of essential genes identified in human osteosarcoma cells, PLK1, a cell cycle master regulator, stood out as the top hit." (PMID 37419907, 2023). "To provide preclinical proof-of-concept therapeutic actionability of PLK1 inhibitor, we further examined the impact of PLK1 inhibition in osteosarcoma PDX models." (PMID 37419907, 2023). "By exploring the human kinome, we discovered a cohort of genes required for human osteosarcoma cells growth and survival, in which PLK1 was the top hit." (PMID 37419907, 2023). "This research aimed at evaluating PLK1 and c‐Myc protein expression in 53 appendicular canine osteosarcoma (cOSA) samples and the in vitro effects of BI 2536 on a c‐Myc and PLK1‐overexpressing cOSA cell line (D17)." (PMID 36054794, 2022). "The gene expression results confirmed that siPLK1 delivered by ALC-PEI significantly reduced the PLK1 mRNA expression in Kirsten human osteogenic sarcoma (KHOS) cells in comparison with the scramble control and free siPLK1." (PMID 35209090, 2022). "Polo‐like kinase 1 (PLK1) is dysregulated in a variety of human cancer types, including osteosarcoma, and induces c‐Myc accumulation." (PMID 36054794, 2022). "In osteosarcoma, polo-like kinase 1 (PLK1, a serine/threonine protein kinase) and MYC promote cell proliferation through the autophagic pathway." (PMID 34445233, 2021). "PLK1 is highly expressed during mitosis, and elevated levels are found in many cancers, including osteosarcoma, whereas depletion of PLK1 in osteosarcoma cells dramatically inhibits cell proliferation and induces apoptosis." (PMID 32944406, 2020). "Pathway integration analysis identified Polo Like Kinase 1 (PLK1)-mediated checkpoint adaptation as critical to the survival of a distinctly aggressive osteosarcoma." (PMID 29100308, 2017).
osteosarcoma (continued). "In osteosarcoma, Plk1 show higher expression in tumor samples compared to normal tissue, and its inhibition with NMS-P397 (not present in our library) leads to growth arrest and apoptosis." (PMID 26807203, 2015). "Polo-like kinase 1 (PLK1), a critical cell cycle regulator, has been identified as a potential target in osteosarcoma (OS)." (PMID 24566468, 2014). "Another study showed that PLK1 promoted osteosarcoma cell proliferation by promoting autophagy." (PMID 40517136, 2025). "We next evaluated the effects of PLK1 knockdown on the invasive capacity of osteosarcoma cells." (PMID 38780513, 2024). "PLK1 was significantly upregulated in osteosarcoma tissues compared to normal controls." (PMID 38780513, 2024). "We next investigated the effects of PLK1 knockdown on osteosarcoma apoptosis." (PMID 38780513, 2024). "Therefore, the PLK1/FBXW7/Myc axis creates a positive auto-regulatory signal crucial in promoting tumorigenesis and underscores PLK1 as potential therapeutic target in Myc-overexpressing tumors, as validated in our previous study on osteosarcoma cell lines." (PMID 38791684, 2024). "Finally, we constructed a subcutaneous xenograft model in vivo to evaluate the potential of hfCas13d‐mediated PLK1 knockdown delivered by lentiviral vectors as a therapeutic strategy for osteosarcoma." (PMID 38780513, 2024). "In addition, we found that PLK1 silencing reduced the invasive capacity of osteosarcoma cells, likely by restoring epithelial characteristics as shown by increased E‐cadherin expression." (PMID 38780513, 2024). "Finally, in vivo delivery of hfCas13d vectors targeting PLK1 substantially attenuated osteosarcoma xenograft growth in nude mice." (PMID 38780513, 2024). "Further optimization of PLK1 suppression approaches may ultimately improve clinical outcomes for osteosarcoma patients." (PMID 38780513, 2024). "In summary, targeted PLK1 inhibition triggers intrinsic apoptotic pathways in osteosarcoma cells." (PMID 38780513, 2024). "Interestingly, PLK1 as the top hit in our screens had been also identified in a parallel screen in 143B, MG-63, and U2OS-MTX300 osteosarcoma cells, thereby confirming the robustness of our identification as well as the important role of PLK1 in osteosarcoma." (PMID 37419907, 2023). "In order to evaluate the clinical significance, we first analyzed PLK1 expression in osteosarcoma." (PMID 37419907, 2023). "Next, we assessed the correlation of PLK1 expression with the prognosis of osteosarcoma patients." (PMID 37419907, 2023). "The acid-labile surface coating MNC@siRNA, composed of tannic acid, serves a dual purpose as both a pore-capping agent to protect PLK1 siRNA and as a pH-responsive switch for on-demand intracellular release of the PLK1 siRNA in the human osteosarcoma KHOS cell line in vitro." (PMID 37242674, 2023). "Similar with the result in osteosarcoma, PLK1 was also upregulated in sarcoma." (PMID 37419907, 2023). "PLK1 has been proposed as a therapeutic target for osteosarcoma." (PMID 37419907, 2023). "In addition, miR-1224-5P in osteosarcoma directly targets PLK1 through the PI3K/AKT signaling pathway to activate autophagy and cell invasion." (PMID 35756492, 2022). "In addition, the kinase Aurora-A and its cofactor Bora are pivotal for Plk1 phosphorylation at Thr-210 during mitosis of human osteosarcoma U2OS cells." (PMID 26242183, 2015). "Additionally, PLK1 protein levels were also upregulated in the osteosarcoma tissues." (PMID 37419907, 2023). "Finally, using a precision medicine approach to integrate functional, transcriptional and mutation data for the exceptionally aggressive osteosarcoma PCB151JAX, we identified the PLK1 pathway as the most aberrant pathway with potential for therapeutic targeting." (PMID 29100308, 2017). "For instance, research on PLK1, a kinase involved in cell cycle regulation, and the use of the U2OS osteosarcoma cell line help garner insights into autophagic regulation across different cancer types." (PMID 39655055, 2024).
osteosarcoma (continued). "PLK1 knockdown significantly reduced matrix metalloproteinase‐2 (MMP2) mRNA and protein levels in osteosarcoma cells." (PMID 38780513, 2024). "SRSF3 has been recently reported to regulate alternative splicing and gene expression of forkhead box M1 (FoxM1), polo-like kinase 1 (PLK1), and cell division cycle 25B (Cdc25B) in U2OS osteosarcoma cells." (PMID 28039456, 2017). "Checkpoint adaptation was in fact first described in human cells using the osteosarcoma cell line U2OS, where cell cycle progression despite DNA double-strand breaks was shown to depend on PLK1." (PMID 29100308, 2017). "Polo-like kinase 1 (PLK1) is a key component in cell cycle regulation, and has been identified as a potential target of osteosarcoma (OS)." (PMID 24566468, 2014). "The overexpressed kinases in osteosarcoma, liposarcoma, and leiomyosarcoma are mainly serine/threonine kinases (BUB1, CKD4, HUNK, LKKK1, NEK2, PBK, PLK1, and PLK4), whereas TTK has a dual role (Tyrosine and serine/threonine kinase) and only MELK presents tyrosine phosphorylation activity." (PMID 40723917, 2025). "Interestingly, PLK1 silencing markedly increased Smad2 and Smad3 phosphorylation in both MG‐63 and U2OS osteosarcoma cell lines." (PMID 38780513, 2024). "As PLK1 inhibitors are entering phase III clinical trials, our findings provide important insights into the efficacy and MoA of the relevant therapeutic approach for combating osteosarcoma." (PMID 37419907, 2023). "Myc stabilization by PLK1 also plays a prominent role in maintaining the autophagy pathway in tumour cells: knockdown of PLK1 leads to a significant reduction in c-Myc protein levels, impacting on MYC transactivation and impairing Myc-mediated autophagy in osteosarcoma cells." (PMID 36902175, 2023). "Two hits from our screen, PLK1 and ILK, have been reported to be oncogenes in osteosarcoma." (PMID 32944406, 2020). "Targeting checkpoint adaptation in osteosarcoma has not been pursued to date clinically, but may be feasible now that PLK1 inhibitors are entering clinical trials." (PMID 29100308, 2017).
triple-negative breast carcinoma (30 papers, 2012 to 2025). An invasive breast carcinoma which is negative for expression of estrogen receptor (ER), progesterone receptor (PR), and human epidermal growth factor receptor 2 (HER2). "Notably, elevated PLK1 expression is associated with aggressive tumor characteristics in Triple Negative breast cancer (TNBC)." (PMID 37893423, 2023). "PLK-1 is associated with tumor cell growth and division for triple negative breast cancer." (PMID 32580326, 2020). "Recent studies have shown that inhibition of kinases related to cell cycle check points, including checkpoint kinase 1 (CHK1), polo-like kinase 1 (PLK1), or aurora kinase A or B, exhibits synthetic lethality in combination with RB deficiency in triple-negative breast cancer (TNBC) or SCLC." (PMID 32244804, 2020). "In triple-negative breast cancer, high KIF4A expression is linked to increased sensitivity to PLK1 inhibitors, such as GSK461364138." (PMID 41361459, 2025). "PLK1 was enriched in the triple-negative breast cancer (TNBC) subtype and exhibited poor overall survival (p = 0.0347)." (PMID 38234395, 2023). "Inhibition of PLK1 overcomes therapeutic resistance to BET inhibitors in triple-negative breast cancer." (PMID 35910374, 2022). "In a triple negative breast cancer, the PLK1 inhibitor BI2536 impaired tumor growth also in vivo as single agent, but when combined with doxorubicin and cyclophosphamide this treatment gave a faster complete response and prevented relapses." (PMID 35719948, 2022). "A similar nanosystem was also used for the targeted delivery of siRNA against Polo-like kinase 1 (PLK1) in a triple-negative breast cancer (TNBC) model." (PMID 32660110, 2020). "Markers for cell proliferation like Top2a, Birc5, and Mki67 are highly expressed, so are markers for metastasis like Msln, Ect2, and Plk1, which are known to be overexpressed in triple-negative breast cancer (TNBC)." (PMID 32793490, 2020). "Inhibition of Plk1 in combination with taxanes shows promising results in a subset of triple negative breast cancer intrinsically resistant to chemotherapy." (PMID 31751384, 2019). "The pharmacological inhibition of PLK1 in triple-negative breast cancer has been reported to increase the anti-proliferative activity of drug-resistant cells, which in turn causes G2/M phase block and increases the phosphorylation of cell cycle proteins inducing apoptosis." (PMID 34996995, 2022). "Therefore, we sought to develop a PLK1 allosteric inhibitor targeting the PLK1 T-loop (a switch responsible for activation) and evaluate its effects in triple-negative breast cancer cells." (PMID 35454120, 2022). "Targeting of PLK1 using the BI2536 inhibitor in combination with conventional chemotherapy was recently shown to impair tumor growth in vivo in two xenografts models established from biopsies of triple negative breast cancer patients." (PMID 24525428, 2014). "PLK1 and AURKB mediated survivin phosphorylation promotes triple-negative breast cancer proliferation." (PMID 38351178, 2024). "We assessed the activity of two ATP-competitive Plk1 inhibitors, GSK461364 and onvansertib, alone and with a taxane in a set of triple negative breast cancer cell lines and in vivo." (PMID 31751384, 2019). "JQ1 also synergistically reduced proliferation of triple-negative breast cancer (TNBC) cells with volasertib, an inhibitor of PLK1 (PLK1 is overexpressed in TNBC) and decreased the expression of stem cell markers." (PMID 30906568, 2019). "Our studies, however, do not contest the possible role of Tex14 in mediating REST turnover; the formation of an STP complex; or the possibility of SCYL1, Tex14, PLK1, and REST being aberrantly expressed in triple-negative breast cancer cells." (PMID 28570664, 2017).
liver cancer (28 papers, 2012 to 2025). An epithelial or non-epithelial malignant neoplasm that arises from the liver. "PLK1 overexpression in liver cancer is associated with tumour progression, metastasis, and vascular invasion." (PMID 37648284, 2023). "Among them, MCODE 1 mainly comprised the mutations of CDK1, KIF2C, KIF18A, CENPA, and PLK1, which take part in the tumorigenesis and progression of liver cancer." (PMID 34414037, 2021). "GSEA results showed that ECT2 was significantly associated with pathways linked to liver cancer-related pathways and the PID_PLK1 pathway." (PMID 33558466, 2021). "The oncological potential of plk1 has been recognized especially in gastric, breast and liver cancers and has led to efforts to develop cancer treatments and drugs based on the inhibition of its action as an oncogene." (PMID 40430225, 2025). "IRE1α overexpression can significantly downregulate the level of Polo-like kinase 1, thereby exacerbating the apoptosis level of liver cancer cells." (PMID 39997944, 2025). "Our previous studies have demonstrated that inhibiting PLK1 significantly impedes the cell cycle and proliferation of liver cancer cells." (PMID 38255993, 2024). "Studies have shown that knocking down the PLK1 gene can significantly inhibit the migration of human liver cancer vascular endothelial cells." (PMID 38816744, 2024). "Our findings implicate PLK1-induced β-actin remodelling as an important mechanism in HCV-induced liver cancer progression." (PMID 37648284, 2023). "This study identifies PLK1 as a novel protein that promotes liver cancer in people with hepatitis C. The findings suggest a novel drug target for patients with liver cancer to reduce cancer spread and improve survival." (PMID 37648284, 2023). "Our study used a mouse liver cancer model based on HTVi to confirm the relationship between mir-100 and PLK1 in vivo quickly." (PMID 38201556, 2023). "A hydrodynamic transfection liver cancer mouse model was employed to verify the interaction between hsa-miR-100-5p and PLK1 further in vivo." (PMID 38201556, 2023). "In this study, utilizing public data from clinical cohorts and functional genetic screens, we comprehensively investigated the potential therapeutic role of PLK1 in liver cancer." (PMID 34522226, 2021). "Accordingly, the target PLK1 was selected for further validation of its therapeutic potential in liver cancer." (PMID 34522226, 2021). "As expected, the experimental results showed a good agreement with the computational results, collectively demonstrating that inhibition of PLK1 has the potential to be a novel and selective anti-liver cancer strategy." (PMID 34522226, 2021). "Overall, the consistent results from in silico prediction and in vitro experiments demonstrate the potential of targeting PLK1 for treating liver cancer." (PMID 34522226, 2021). "The significant clinical implications and the high cell dependencies both suggest that PLK1 can be a promising therapeutic target in liver cancer." (PMID 34522226, 2021). "Of note, high expression of FoxM1 and its downstream effector factors (Plk1, CyclinB1, Skp2 and Aurora B Kinase) correlated with poor overall survival in hepatic cancer patients (analyzed from RNA-seq data available on Kaplan-Meier plotter)." (PMID 34900697, 2021). "For the first time, we found a significant positive correlation between DLAT expression and m6A regulatory factors in liver cancer, and that DLAT is associated with the PLK1 pathway, PI3K-AKT signaling pathway, Notch signaling pathway, WNT signaling pathway, and Aurora B pathway." (PMID 40302799, 2025).
liver cancer (continued). "Using mouse liver cancer models, these results provide valuable insights for future rapid gene interaction studies and further validation of the relationship between hsa-miR-100-5p and PLK1." (PMID 38201556, 2023). "Hepatitis C virus (HCV) NS5A protein stimulates PLK1-mediated phosphorylation of host proteins, so we hypothesised that HCV–PLK1 interactions might be a mechanism for HCV-induced liver cancer." (PMID 37648284, 2023). "CCNB2 may responsible for the initiation and progression of liver cancer through the CCNB2/PLK1 pathway and increase the growth and migration of liver cancer cells." (PMID 34838000, 2021). "Additionally, a novel therapeutic strategy targeting PLK1 was also demonstrated to have significant potential in the field of personalized liver cancer treatment." (PMID 34522226, 2021). "The relationship between PLK1 and liver cancer has recently been confirmed." (PMID 33952716, 2021). "In summary, these data indicated that both PLK1 and HRAS expression levels increase during HCC development and remain elevated in (advanced) liver cancer in vitro and in vivo." (PMID 29423069, 2018). "Taken together, these results suggest that galangin may induce apoptosis in liver cancer cells by disrupting the cell cycle through its influence on cell cycle proteins such as CCNB1, CDK4, CDK1, and PLK1." (PMID 38816744, 2024).